MIR450B (microRNA 450b)
Synonyms: hsa-mir-450b; MIRN450B; mir-450b
Gene: MicroRNA gene on chromosome X (134,540,185 to 134,540,262, reverse strand). Ensembl gene ENSG00000216001.
Gene Ontology:
Biological process: miRNA-mediated post-transcriptional gene silencing
Cellular component: RISC complex
Homologues: Orthologues: chimpanzee ptr-mir-450b (100% identical), macaque mml-mir-450b (97% identical), guinea pig MIR450B (95% identical), pig ssc-mir-450b (94% identical), mouse Mir450b (88% identical). Paralogues in human: MIR450A2 (87% identical), MIR450A1 (81% identical).